ANXA3 (annexin A3)
Diseases named in the same sentence as ANXA3 in open-access papers (continued):
Sharing a sentence is not in itself a finding about the gene and the disease.
breast cancer (continued). "An elevated expression of ANXA3 was detected in breast cancer samples, compared to adjacent tissue samples, and significant correlation depending on the number of lymphatic metastases (P = 0.001) and histological grade (P = 0.004) was observed." (PMID 28497041, 2017). "Further subgroup analyses revealed that the positive expression rate of ANXA3 in patients with triple-negative breast cancer (TNBC) (79.66%) was significantly higher than that in patients with other types of breast cancer (χ2 = 9.226; P = 0.026)." (PMID 28497041, 2017). "In the current study, differential expression of ANXA3 in different subtypes of breast cancer was detected by immunohistochemistry." (PMID 28497041, 2017). "Following an extensive verification phase, a potential new breast cancer serum biomarker was detected and subsequently identified as human Annexin A3 (ANX A3), a phospholipid and calcium binding protein." (PMID 26093083, 2015). "Interestingly, a research on breast cancer has described an opposite correlation; the depletion of ANXA3 using short hairpin RNA plasmids has been shown to promote cell proliferation in both cell-line models and mouse xenograft models." (PMID 34355022, 2021). "Moreover, a Max Vision immunohistochemistry-based retrospective analysis of a cohort of 309 breast cancer patients demonstrated that ANXA3 expression in triple negative breast cancer (TNBC) patients was significantly higher than other breast cancer subtypes." (PMID 34355022, 2021). "ANXA3 could affect breast cancer cell proliferation and invasion by regulating the transition between mesenchymal-like state BCSCs and epithelial-like state BCSCs via the NFκB pathway." (PMID 29374148, 2018). "Next, to ascertain whether the ANXA3 knockdown influenced the sensitivity of breast cancer cells to Dox in vivo, the 4T1 tumor model was utilized." (PMID 29374148, 2018). "In addition, we systematically studied the effect of ANXA3 on breast cancer in vitro and in vivo, and this is the first investigation of the effect of ANXA3 on BCSCs." (PMID 29374148, 2018). "This study described the role and mechanisms of ANXA3 in regulating BCSCs and breast cancer growth and metastasis, indicating that downregulating ANXA3 together with chemotherapy might be a novel therapeutic strategy for treating breast cancer." (PMID 29374148, 2018). "As recent studies have shown that high ANXA3 expression is involved in resistance to chemotherapy reagents in several cancers, we investigated the effect of ANXA3 on chemotherapy sensitivity in breast cancer cell lines." (PMID 29374148, 2018). "In addition, we demonstrated that ANXA3 knockdown increased the sensitivity of breast cancer cells to doxorubicin by increasing the drug uptake." (PMID 29374148, 2018). "However, the function of ANXA3 in breast cancer remains to be elucidated, and the effect of ANXA3 on regulating BCSCs has not been investigated." (PMID 29374148, 2018). "The present study evaluated the potential of ANXA3 as a biomarker for breast cancer." (PMID 28497041, 2017). "The data indicate a potential role of ANXA3 in promoting metastasis in breast cancer." (PMID 28497041, 2017). "Hence, combined with our observation, ANXA3 can be viewed as a potential biomarker for the determination of infiltration, metastasis, and prognosis of breast cancer." (PMID 28497041, 2017). "Therefore, in this study, immunohistochemical investigation for differential expression of ANXA3 in breast cancer tissue of different subtypes was determined to validate its correlation with the clinicopathological features and prognosis of breast cancer." (PMID 28497041, 2017). "The ANXA3 expression rate in breast cancer tissues was 64.25%." (PMID 28497041, 2017). "Therefore, the findings are supportive for the correlation of ANXA3 expression with prognosis in breast cancer." (PMID 28497041, 2017). "The study validates the use of ANXA3 as a potential prognosis biomarker for breast cancer." (PMID 28497041, 2017).
breast cancer (continued). "However, the number of lymphatic metastases and ANXA3 expression were identified as the independent risk factors affecting DFS and OS of patients with breast cancer, respectively." (PMID 28497041, 2017). "Thereby, further studies on the prognostic value of ANXA3 in breast cancer are needed." (PMID 28497041, 2017). "Additionally, ANXA3 is related to drug resistance in breast cancer." (PMID 41007650, 2025). "However, the role of ANXA3 in breast cancer is still unclear." (PMID 29374148, 2018). "However, analysis of ANXA3 expression in breast cancers of different molecular subtypes revealed significantly (P = 0.026) higher levels of ANXA3 in triple-negative breast cancer compared to those in the three other groups (Luminal A, Luminal B, and HER-2 positive types)." (PMID 28497041, 2017). "Gene of Ccl17, Cxcl13, Cxcr3, IFN-γ, and Sema3a, were significantly decreased while the Anxa3 and Nr4a1 were significantly upregulated in SB2−/−;PyMT mammary tumors." (PMID 35768767, 2022). "For example, in vitro investigations on breast cancer cell lines HCC-1954 and MDA-MB-231 demonstrated that ANXA3 silencing using siRNA significantly reduced the expression of CDK4 and enhanced the expression of E2F1 and p27Kip1." (PMID 34355022, 2021). "In conclusion, our study showed that there is a negative correlation between ANXA3 expression and breast cancer prognosis." (PMID 29374148, 2018). "Furthermore, we found that ANXA3 knockdown inhibited the NFκB pathway via upregulating IκBα, resulting in mesenchymal–epithelial transition (MET) and a heterogeneity change of breast cancer stem cells (BCSCs)." (PMID 29374148, 2018). "However, ANXA3 has not been well studied in breast cancer, and the biological role of ANXA3 is still unclear." (PMID 29374148, 2018).
colorectal cancer (13 papers, 2013 to 2023). A primary or metastatic malignant neoplasm that affects the colon or rectum. "For example, miR-340-5p was lower expressed in colorectal cancer and acted as a tumor suppressor in colorectal cancer by binding ANXA3." (PMID 33661995, 2021). "ANXA3 expression has been previously observed to correlate significantly with tumor growth and poor prognosis in colorectal cancer." (PMID 29423100, 2018). "An upregulation of ANXA3 by 63% was reported in patients with colorectal cancer and a significant upregulation of ANXA3 was detected in the blood of colorectal cancer patients." (PMID 28497041, 2017). "Levels of ANXA3 expression have shown significant differences in colorectal cancer, pancreatic cancer, lung cancer, and hepatocellular carcinoma." (PMID 28497041, 2017). "S100 calcium-binding protein A9, annexin A3, nicotinamide phosphoribosyltransferase, carboxylesterase 2 and calcium activated chloride channel A1 were probably potential biomarkers of colorectal cancer." (PMID 27661117, 2016). "In the present study, 65 and 47% of colorectal cancer specimens were found to show Annexin A3 and HIF-1α immunoreactivity, respectively." (PMID 24260057, 2013). "Cox regression analysis revealed that Dukes’ stage, lymph node metastases and Annexin A3 expression were independent prognostic factors in colorectal cancer patients." (PMID 24260057, 2013). "The results indicate that the increased expression of Annexin A3 in colorectal cancer significantly correlates with tumor progression and poor prognosis." (PMID 24260057, 2013). "In conclusion, the present study is the first to evaluate Annexin A3 expression and its correlation with clinicopathological factors in colorectal cancer tissues." (PMID 24260057, 2013). "The results of the current study indicated for the first time that the increased expression of Annexin A3 in colorectal cancer correlates significantly with tumor growth and poor prognosis." (PMID 24260057, 2013). "These contradictory studies led the present study to investigate the roles of Annexin A3 expression in colorectal cancer." (PMID 24260057, 2013). "Univariate and multivariate analyses were performed to evaluate the impact of Annexin A3 expression and pathological factors on the prognosis of colorectal cancer." (PMID 24260057, 2013). "Similarly, ANXA3 was overexpressed in colorectal cancer (CRC) tissues compared to adjacent normal tissues, as shown from immunohistochemistry and western blot results." (PMID 34355022, 2021). "Of the 60 colorectal cancer tissues, Annexin A3 staining was undetected in 21 cases." (PMID 24260057, 2013). "The objective was to ascertain whether Annexin A3 is involved in the progression of colorectal cancer, and to investigate its correlation with HIF-1α." (PMID 24260057, 2013). "In total, 60 colorectal cancer samples were detected for Annexin A3 and HIF-1α staining." (PMID 24260057, 2013). "We hypothesized that Annexin A3, a member of the Annexin family, and HIF-1α may be associated with each other in colorectal cancer." (PMID 24260057, 2013). "Furthermore, the high expression of Annexin A3 in colorectal cancer tissues was found to significantly correlate with shorter overall survival in patients, compared with that of low Annexin A3 expression." (PMID 24260057, 2013). "Support on this finding was delivered by in vitro data of colorectal cancer, in which the phosphorylation of ERK and JNK was found to be significantly reduced once a depletion of ANXA3 was established using small interfering RNA (siRNA)." (PMID 34355022, 2021). "Furthermore, overexpression of Annexin A3 was found to significantly correlate with tumor size and Dukes’ stage, which indicated that Annexin A3 expression may be important in the development of colorectal cancer." (PMID 24260057, 2013).
colorectal cancer (continued). "The expression of Annexin A3 and HIF-1α in 60 colorectal cancer tissues was assessed by immunohistochemistry to statistically analyze the association between the clinicopathological features and survival of these cases." (PMID 24260057, 2013). "In the present study, a subset of the colorectal cancer cases with follow-up data were analyzed to show a correlation between the absence of Annexin A3 and clinical outcome." (PMID 24260057, 2013). "In this study, the expression of Annexin A3 and HIF-1α was detected in colorectal cancer." (PMID 24260057, 2013). "In addition, Annexin A3 and HIF-1α proteins appear to be important in the advancement of colorectal cancer." (PMID 24260057, 2013). "The results indicated that Annexin A3 protein expression was significantly increased in colorectal cancer tissues compared with the paired noncancerous tissues, which is consistent with the results in lung adenocarcinoma." (PMID 24260057, 2013). "Furthermore, Annexin A3 and HIF-1α protein expression exhibited a similar pattern in these samples, and their expression was found to correlate with poor survival in colorectal cancer patients." (PMID 24260057, 2013). "Compared with weak or no expression in normal colorectal tissues, 65% (39/60) of colorectal cancer specimens showed Annexin A3 immunoreactivity." (PMID 24260057, 2013). "However, to date, a correlation between Annexin A3 expression and colorectal cancer has not been reported." (PMID 24260057, 2013).
lung carcinoma (11 papers, 2017 to 2025). "In lung cancer, cancer associated fibroblasts (CAFs) increased AnxA3 levels in the neighbouring cancer cells, which correlated with increased cisplatin resistance." (PMID 33810523, 2021). "Our previous study also demonstrated that CAFs contribute to cisplatin resistance via modulating ANXA3 in lung cancer cells." (PMID 40959099, 2025). "Further mechanism study illustrated that CAFs decreased the chemo-sensitivity of lung cancer cells through inhibiting cisplatin-induced apoptosis by activating ANXA3/JNK signaling pathway." (PMID 40959099, 2025). "The crosstalk was demonstrated using CAF-CM (CAF-conditioned media) incubation, which increased the ANXA3 level in lung cancer cells, which subsequently enhanced cisplatin resistance by inhibiting cisplatin-induced apoptosis involving ANXA3/JNK signaling." (PMID 35326670, 2022). "In lung cancers, CAFs have been reported to express a higher level of annexin A3 (ANXA3) than normal fibroblasts." (PMID 35326670, 2022). "ANXA3 expression in lung cancer tissue with lymphatic metastasis was detected to be significantly higher in comparison to lung cancer tissue with the absence of lymphatic metastasis." (PMID 28497041, 2017). "In contrast, AnxA3 knockdown in this model increased cisplatin sensitivity, an observation that may add to overcome drug resistance in lung cancer patients." (PMID 33810523, 2021). "Another preclinical study showed that annexin A3 (ANXA3) overexpression in CAFs activated the JNK pathway, which inhibited cisplatin-induced apoptosis in lung cancer cells." (PMID 39757995, 2025). "Similar to this study, a significant upregulation of ANXA3 has been identified in CRC tissues compared with normal mucosa as well as in several other cancers, such as pancreas, breast, and lung cancers." (PMID 33672900, 2021). "ANXA3 expression was also found to be higher in lung cancer patients with lymph node metastases than those without metastases." (PMID 36936694, 2023).
Sepsis (11 papers, 2020 to 2025). Sepsis is defined as life-threatening organ dysfunction caused by a dysregulated host response to infection. "We think that it might be worth investigating a possible role for ANXA3 in extending neutrophil longevity — a phenomenon that has been observed during sepsis and is implicated in end‐organ damage." (PMID 32682335, 2020). "The role of annexin A3 (ANXA3) in regulating endothelial permeability and inflammation during sepsis is explored using ANXA3 knockout mice and primary human umbilical vein endothelial cells (HUVECs)." (PMID 40151887, 2025). "As mentioned in one literature review, ANXA3 was also up-regulated in sepsis, but its role is unclear." (PMID 38166628, 2024). "ANXA3 upregulation in sepsis is also observed in the whole blood of patients presenting with different degrees of disease severity and across all age groups, from infancy to adulthood." (PMID 32682335, 2020). "Annexin A3 transcript abundance seems to be robustly increased during sepsis and after exposing neutrophils to septic plasma in vitro." (PMID 32682335, 2020). "Specifically, the expression levels of these 4 genes were increased > 4.0-fold in patients with sepsis compared with those in healthy subjects: ANXA3 (28.1-fold), S100A8 (4.9-fold), S100A9 (4.4-fold), and MMP9 (69.2-fold)." (PMID 32922168, 2020). "On the basis of these findings, we infer a possible role for ANXA3 in mediating neutrophil microbicidal function and pathogen clearance during sepsis." (PMID 32682335, 2020). "More relevant to the sepsis profiling data presented and discussed here, mechanistic studies point to a role played by ANXA3 in promoting cancer growth and metastasis." (PMID 32682335, 2020). "We consider that our observations provide sufficient grounds for revisiting and further characterizing the role of ANXA3 in neutrophils, and especially in the context of sepsis." (PMID 32682335, 2020). "This review article intends to explore a possible role for Annexin A3 (ANXA3) in the immunopathology of sepsis." (PMID 32682335, 2020). "Overall, the synthesis of available public data points to a robust increase in ANXA3 abundance in the context of sepsis." (PMID 32682335, 2020). "The level of ANXA3 expression was significantly increased in patients with sepsis, indicating its function in limiting the formation and expansion of thrombosis." (PMID 32922168, 2020). "Thus, ANXA3 stabilizes the actin cytoskeleton, playing a protective role in endothelial dysfunction during sepsis." (PMID 40151887, 2025). "In agreement with our findings, one Chinese prospective cohort study also performed a comprehensive transcriptome profile analysis and qPCR validation, and suggested S100A8, S100A9, and ANXA3 as key genes differentially expressed between sepsis patients and healthy controls." (PMID 37298316, 2023). "Moreover, a recent meta-analysis of public transcriptome data found that ANXA3 expression is almost completely restricted to neutrophils and that its gene expression level, as well as plasma levels, are increased in sepsis patients." (PMID 34966382, 2021). "Furthermore, we showed that annexin A3 levels on circulating neutrophils can be used as a predictor of early sepsis mortality in ICU." (PMID 34966382, 2021). "Taken together, this literature might provide sufficient ground to explore a possible role of ANXA3 in the regulation of neutrophil survival, which may have a direct implication on survival in the context of sepsis." (PMID 32682335, 2020). "Our analysis of public transcriptome data supports that ANXA3 transcript abundance is significantly increased in the blood in patients with sepsis; our hypothesis now remains to be elucidated via downstream studies and/or experimentation." (PMID 32682335, 2020). "Other parts of the ANXA3 literature may also yield additional clues concerning a role for ANXA3 in sepsis." (PMID 32682335, 2020). "In addition, an increase in ANXA3 transcripts in the blood of sepsis patients has been observed." (PMID 34573352, 2021).